IGF2R (insulin like growth factor 2 receptor)
Diseases named in the same sentence as IGF2R in open-access papers (continued):
Sharing a sentence is not in itself a finding about the gene and the disease.
tumor (110 papers, 1999 to 2026). "Given its role in clearing IGF-2, IGF-2R functions as a tumor suppressor, where the loss of its function can lead to an accumulation of IGF-2, promoting tumorigenesis." (PMID 37834454, 2023). "One of the PNenGs, IGF2R, was a tumor suppressor gene, with a high frequency of loss-heterozygosity (LOH) and protein expression in diverse types of malignant cancer." (PMID 34221990, 2021). "Functionally defining the tumour suppressor function of IGF2R in mouse models in vivo has been dependent on the nature of the Igf2r gain and loss of function alleles, and the types of models used." (PMID 31388182, 2019). "Circumstantial data from sequencing human cancers and genetic modification of cell lines, have implicated IGF2R as a tumour suppressor gene." (PMID 31388182, 2019). "Herein, we report a case of malignant SFT associated with a hypoglycemia attack, and we discuss the associations among IGF2, IGF1R, and IGF2R in SFT based on analyses of the tumor in this case." (PMID 30168002, 2018). "For LUSC1, all the single tumor cells had the clonal mutation (R45P) in Igfbp7 and a subset of single tumor cells had the mutation (R2457S) in Igf2r." (PMID 29484121, 2018). "The loss of IGF2R activity affects tumor growth, apoptosis, angiogenesis, and invasion." (PMID 36330486, 2022). "We also demonstrated that hsa_circ_0007813 knockdown could hinder autophagy and IGF2R expression, which underlay the tumor inhibitory effect of it." (PMID 34365465, 2021). "Different studies demonstrated that IGF2R expression could be involved in the development of hepatocarcinoma, breast and ovarian human cancers by encoding for a tumor suppressor gene." (PMID 32075092, 2020). "By performing scRNAseq on CT26 MMRd tumor cells alone, we observed that the expression of Ptprs and Igf2r was significantly decreased after the combination of vaccination and PD-1 blockade compared to anti-PD-1 therapy alone." (PMID 41256707, 2025). "In vivo, the silent IGF2R MSCs were utilized to treat the D12 rats, found that this inhibited the increase of CCA, alleviated the tumor burden and injury of liver, which caused by MSCs." (PMID 39674501, 2025). "A protein that was strongly upregulated exclusively in adult pre-leukemic cells was Igf2r, which is classified as a growth inhibitor and has also been proposed as a target for tumor control." (PMID 38555405, 2024). "Nevertheless, for effective RIT, the high expression of IGF2R in OS is sufficient to deliver cytocidal doses of radiation to the tumor, while sparing normal tissues." (PMID 37570809, 2023). "The role of IGF2R as an oncogene is unclear, with contradicting reports suggesting that it has tumor-suppression activity in certain tumors." (PMID 37570809, 2023). "This is in contrast to the high expression of IGF2R on the surface of human and canine OS tumor cells." (PMID 37513891, 2023). "Though some studies reported increased expression of IGF-2R, the contribution of IGF-2R overexpression to tumor development is still unclear." (PMID 37834454, 2023). "We demonstrated that IGF2R was conspicuously upregulated in LC tumors and validated our results by revealing the correlations between IGF2R expression and the tumor microenvironment and immune cell infiltration." (PMID 36299463, 2022). "Their results demonstrated that the effect of immunotherapy is significant only when increased levels of IGF2R are present on the surface of tumor cells." (PMID 36299463, 2022). "In our study, a significant correlation was observed between IGF2R expression and the stromal score, indicating a potential regulatory effect of IGF2R on the tumor microenvironment and LSCC progression." (PMID 36299463, 2022). "IGF2R inhibits the proliferation of T cells and the infiltration of T cells in a tumor by TGFβ activation." (PMID 36330486, 2022). "Several studies reported that overexpression of full-length IGF2R decreases cell growth and decreases tumor growth in vivo." (PMID 35216324, 2022).
tumor (continued). "In this study, a systematic evaluation was conducted to define the relationship between IGF2R expression and the tumor microenvironment, immune cell infiltration, and immune checkpoint molecules." (PMID 36299463, 2022). "In accordance with the result that IGF-2 promotes the growth and proliferation of tumor cells, IGF-2R is considered to be a tumor suppressor gene during cancer occurrence and development." (PMID 36358907, 2022). "IGF2R, represented as a type I transmembrane glycoprotein expressed ubiquitously in human tissues, is capable to inhibit tumor growth through binding to a wide range of ligands." (PMID 36406134, 2022). "The most frequently mutated genes in the tumor fragments of women were USH2A, ATM, and IGF2R; in female dogs, they were USH2A, BRCA2, and RRM2." (PMID 34680380, 2021). "As our results proved the regulatory axis of hsa_circ_0007813/hsa-miR-361-3p/IGF2R, it was adequate to explain the tumor-promoting and autophagy-promoting effects of hsa_circ_0007813." (PMID 34365465, 2021). "In this study, we found that knockdown of hsa_circ_0007813 led to decreased IGF2R expression level, thus leading to decreased tumor proliferation, migration, and invasiveness, as well as autophagy." (PMID 34365465, 2021). "Specific IGF2R activation seems less likely to trigger oncogenic processes; moreover, some studies point to the role of IGF2R as a tumor suppressor." (PMID 33673334, 2021). "The M6P/IGF2R is a multiple ligand-binding cell surface receptor, with reported tumor suppressor properties in several cancer entities." (PMID 32385587, 2021). "The IGF-2R/M6PR, which is considered to act as a tumor growth suppressor, has two forms: a membrane-associated and a soluble one, both of which interact with several ligands, including IGF-2, TGFβ and lysosomal enzymes." (PMID 33946484, 2021). "IGF2R, also known as cation-independent mannose-6-phosphate receptor (CI-M6PR), was discovered to participate in both autophagy and tumor biology." (PMID 34365465, 2021). "A novel murine anti-IGF2R mAb, named 2G11, was (radio)labeled with Indium-111 to determine biodistribution and tumor uptake in OS tumor bearing SCID mice." (PMID 34440182, 2021). "In 96 tumours investigated by high‐coverage exome sequencing, we detected missense mutations in: IGF1R (n = 1), IGF2R (n = 1) and IGFBP5 (n = 2)." (PMID 33295144, 2021). "The most frequent top mutated genes in tumor fragments of women were USH2A, ATM, IGF2R, MKI67, and MAP3K1 (median variants per sample = 20; missense, nonsense, and splice site mutations)." (PMID 34680380, 2021). "CIN tumors can be recognized by the accumulation of mutations in tumor-suppressor genes (i.e., transforming growth factor beta receptor 2 (TGFRII), Insulin-like growth factor 2 receptor (IGF2R) and Bcl-2-associated X protein (BAX))." (PMID 32481530, 2020). "Outside of the developmental context, CIM6P/IGF2R plays important roles in growth inhibition, including tumor suppressor functions." (PMID 32369018, 2020). "Some studies have explained the tumor suppressive functions of IGF2R by its negative regulation of the oncogenic IGF2–IGF1R signal axis." (PMID 32075092, 2020). "To evaluate Igf2r tumour suppressor function, we utilised intestinal adenoma models known to be Igf2 dependent." (PMID 31388182, 2019). "Loss of heterozygosis at the locus of IGF2R gene has been reported to be a frequent event in ACC, supporting a potential role of IGF2R as a tumor suppressor gene also in ACC development." (PMID 30838516, 2019). "In order to further evaluate the potential tumour suppressor function of Igf2r dependent IGF2 regulation, we utilised Igf2rI1565A/+p in a human early stage cancer mouse model." (PMID 31388182, 2019).
tumor (continued). "Previously, we have used a xenograft OS mouse model to demonstrate the preferential localization of an IGF2R-radiolabeled monoclonal antibody (mAb) to tumor when compared with its isotype control." (PMID 31391495, 2019). "As 2G11 stays in circulation for several days, it upregulates the IGF2R expression in the tumor and the spleen, which results in its increased uptake in those tissues." (PMID 31391495, 2019). "An intermediate to high staining for IGF2 (82%; median score 5; range 3–6) and IGF1R (65%; median score 4; range 2–6) was observed in most tumor tissues and for IGF2R (median score 5; range 4–6) in all ACCs." (PMID 30838516, 2019). "Further, exogenous rIGF‐2 was able to restore migration in IGF‐2R‐RNAi‐transfected MSCs, but not in IGF‐1R‐RNAi‐transfected cells, demonstrating that IGF‐1R is probably more important for MSC tumor tropism than IGF‐2R." (PMID 29321953, 2018). "IGF2R is also a tumor suppressor involved in multiple cancers and functions in HCC by inhibiting liver cell invasion." (PMID 29416609, 2018). "Although deregulation of IGF pathway through amplification or overexpression of IGF2 is involved in another mucosal-origin tumor, CRC, clinical relevance of IGF2R mutations is still controversial." (PMID 30373548, 2018). "Studies have shown that M6P/IGF-2R gene functions as a tumour suppressor in human liver carcinogenesis." (PMID 25866791, 2015). "The M6P (mannose 6-phosphate)/IGF2R (insulin-like growth factor II receptor) interacts with avariety of factors that impinge on tumour invasion and metastasis." (PMID 23347038, 2013). "It has alsobeen suggested that M6P/IGF2R restricts tumour progression by modulation of latent TGF-βactivation at the cell surface." (PMID 23347038, 2013). "The tumour-suppressive potentialof M6P/IGF2R is supposed to rely largely on its dampening impact on IGF-II signalling." (PMID 23347038, 2013). "This agrees with the fact that IGF-2R functions as a tumor suppressor to sequester IGF-2 from circulation." (PMID 22720981, 2012). "The Tests of Normalityb of IGFBP-2 and IGF-2R in 25 pairs of tumor (T) and paratumorous (P) tissues." (PMID 23071652, 2012). "We then detected the protein expression of IGF-1R, IGF-2R, ERα and ERβ on 80 tumor samples from patients with EAC, 33 samples from patients with atypical hyperplasia, 22 samples from control patients, using immunohistochemistry." (PMID 22720981, 2012). "IGF-2R, also mannose-6-phosphate receptor, is considered a tumor suppressor because it clears IGF-2 from the cell surface to attenuate signaling and loss of function mutations in IGF-2R has been identified in human cancers." (PMID 23071652, 2012). "Collectively, our results thus indicate that reconstitution of functional M6P/IGF2R expression interferes with FRL14 tumor progression." (PMID 22521359, 2012). "We revealed that LOH incidence in the primary tumor at marker D6S1581 (directed proximal to M6P/IGF2R locus) is predictive for the presence of disseminated tumor cells (DTC) in the bone marrow (BM) before surgery and after chemotherapy." (PMID 22849543, 2012). "Contrary to parental FRL14 cells (tumors/injections: 9/9; tumor weight: 13–219 mg; median: 48 mg), tumor formation by FRL14/IGF2R wt cells was reduced and the tumors were smaller (tumors/injections: 5/9; tumor weight: 0–100 mg; median: 18 mg)." (PMID 22521359, 2012). "Nussbaum and colleagues have reported that IGF-2 and its receptor IGF-2R stimulate tumor cell migration in human hepatocarcinogenesis." (PMID 20569443, 2010). "Reduced transcriptional activity of the M6P/IGF-2R promotor was observed in several human and rodent tumour cell lines." (PMID 12618883, 2003). "More importantly, IGF2 secreted by Scissor+ tumor cells could act on themselves through IGF2-IGF1R/IGF2R interactions." (PMID 40098972, 2025). "Furthermore, miR-211 was found to target tumor suppressor IGF2R, resulting in the increase of collagen by CAFs so as to promote tumor cell motility." (PMID 37575250, 2023).
tumor (continued). "Concordantly, the tumor suppressor IGF2R was decreased in metastatic tissues." (PMID 37248468, 2023). "In addition, IGF2R has been shown to promote the secretion of IL-10 by B cells, and IL-10 directly activates or expands T cells in a tumor." (PMID 36330486, 2022). "IGF2R expression was consistent with the expression pattern of these biomarkers, suggesting that IGF2R may potentially promote tumor EMT via the IGF2/IGF2R signaling pathway." (PMID 36299463, 2022). "Regarding autophagy has a dominant role in the survival of tumor cells overcoming cellular stress and correlates with tumor progression, investigations were made to prove that hsa_circ_0007813 could regulate IGF2R expression via hsa-miR-361-3p sponging." (PMID 34365465, 2021). "Although these late reports associate CREG1 functions with downstream signaling pathways, its tumor-suppressor-like functions might reside in its binding to the cation-independent mannose-6-phosphate insulin-like growth factor 2 receptor (M6P/IGF2R)." (PMID 32385587, 2021). "Additionally, the inactivation of M6P/IGF2R occurred in the early stage of hepatocarcinogenesis, which supports the role of M6P / IGF2R as a tumor suppressor gene." (PMID 33495404, 2021). "Furthermore, we also demonstrated IGF2R was correlated with a poor prognosis and was upregulated in tumor tissues compared with normal tissues in the TCGA-CESC data set." (PMID 34221990, 2021). "Similarly, the highest expression of C2orf27A and IGF2R was found at tumor grade 3, and the lowest expression of CFB and PON1 was found at grade 4." (PMID 33495404, 2021). "Abnormalities in IGF-II/IGF2R signaling are related to tumor development." (PMID 34365465, 2021). "It was proved that knockdown of IGF2R could suppress tumorigenic properties of the tumor, as well as tumor cell autophagy." (PMID 34365465, 2021). "Loss of CIM6P/IGF2R function is thought to allow abnormally high levels of circulating IGF2 to exert mitogenic effects, presumably acting via its low-affinity receptor IGF1R, resulting in tumor growth." (PMID 32369018, 2020). "Thus, IGF–2R is thought to suppress tumor growth and proliferation by indirectly suppressing IGF-1R activation." (PMID 33143702, 2020). "Down-regulation of IGF2R has been found in some type of cancers and it has been suggested that IGF2R could play a role as a tumor suppressor gene in some malignancies." (PMID 30838516, 2019). "This was also indicative from survival analysis: high IGF2R expression was correlated with poor prognosis in several types of cancers, while IGF2R might function as a tumor suppressor in cancers where high IGF2R expression is correlated with good prognosis." (PMID 31748500, 2019). "OS tumor cells robustly stained using the IGF2R-specific 2G11 mAb for both cases." (PMID 31391495, 2019). "It has been proposed that tumour growth promotion might result because of increased local IGF2 supply, as a result of the specific loss of IGF2 binding to IGF2R." (PMID 31388182, 2019). "Whilst these data support the constitutive tumour suppressor function of Igf2r, it remains unknown what the specific cell type(s) are that express Igf2r in order to regulate tumour suppressor activity." (PMID 31388182, 2019). "Insulin-like growth factor binds to 2 receptors, IGF1R and IGF2R, but IGF2R is a tumor suppressor." (PMID 29241458, 2017). "So, the IGFR2R example shown in the paper is part of such study focusing on the role of this protein in tumour neovascularization and involving the quantitative evaluation of IGF2R expression in the vascular compartment of a large series of tumours (manuscript in preparation)." (PMID 28220842, 2017). "This expanded model incorporated the IGF2 axis of the IGF network (i.e., IGF2 and IGF2R) and was used to assess the hypothesized roles of IGF2R and IGFBPs as tumor suppressors." (PMID 26861122, 2016). "Likewise, Igf2r was expressed in Tumor and Epithelial/Tumor cell clusters." (PMID 41568176, 2026).
tumor (continued). "However, M6P/IGF2R bindsa variety of other factors that could exert an influence on the proliferation, migration and/orinvasiveness of tumour cells, including heparanase and cysteine cathepsins." (PMID 23347038, 2013). "However, other studies indicate that failure to express M6P/IGF2R may result in an increase of the proteolytic load in the pericellular environment and thus enhance the invasive capacity of tumor cells." (PMID 22521359, 2012). "In the IHC staining of tumor tissue, the CCA-positive area, marked by CK19, CK7, EPCAM, and CD44, in silent IGF2R-MSCs groups were lower than those in the MSCs group." (PMID 39674501, 2025). "Although the rats in the silenced IGF2R-MSCs group showed an aggravated the progression of HCC which compared to PBS group, they exhibited alleviation in the liver injury, tumor burden and the number of dysplastic nodules compared to the MSCs group." (PMID 39674501, 2025). "IGF2R impinges on essential processes in different types of cells, in an opposite way to IGF2; it is thus recognized as a tumor suppressor due to its role in clearing IGF2." (PMID 38612397, 2024). "Many immune-related therapeutic indicators, including PD-1, PD-L1, HER2, IGF2R, CTLA-4, and GD2, are highly expressed in tumor samples." (PMID 36830696, 2023). "Indeed, SpI2-6/IGF2R tumor suppressor functions have been widely demonstrated to be linked to its ability to sequestrate and degrade IGF-II through direct cell internalization, while this does not apply to IGF-I, which displays negligible binding to SpI2-6/IGF2R at physiological concentrations." (PMID 38255147, 2023). "Immunotherapy is also thought to have potential applications in OS and many immune-related therapeutic indicators, including PD-1, PD-L1, HER2, IGF2R, CTLA-4, and GD2, are highly expressed in tumor samples." (PMID 36830696, 2023). "Gene levels corresponding to invasion-related EV proteins showed that five genes (annexin A1, actin-related protein 3, integrin-β1, insulin-like growth factor 2 receptor and programmed cell death 6-interacting protein) were significantly higher in GBM tumours." (PMID 36071478, 2022). "In our differential gene expression analysis and GSEA, most enriched genes are involved in tumor aggressiveness and drug resistance including ABHD2, ABCC4, CLN5 intracellular trafficking protein, and insulin like growth factor 2 receptor." (PMID 35054064, 2022). "Through qRT-PCR on clinical samples, expression of NRP1, IGF2R, SERPINA3 and TNF were significantly upregulated in tumor tissue, while ICOS and DES were significantly downregulated." (PMID 36406134, 2022). "In LSCC patients, a significant positive correlation between IGF2R expression and the stromal score was detected using the ESTIMATE algorithm to estimate the immune score, stromal score, and tumor purity in the tumor microenvironment." (PMID 36299463, 2022). "According to the qRT-PCR results, expression levels of NRP1, IGF2R, SERPINA3 and TNF were significantly upregulated in the comparison between in situ tumor samples and normal tissues in our clinical center." (PMID 36406134, 2022). "IGF2/IGF2-R interaction is key for normal development and is involved in carcinogenesis as well, with IGF2-R reported as an oncogene in some cancers and as tumor suppressor gene in others." (PMID 34940355, 2021). "Treatment of OS tumors using 188Rhenium (188Re) and 177Lutetium (177Lu)-labeled IGF2R-specific mAbs MEM-238 and 2G11 resulted in tumor growth inhibition and possibly regression while being safe to normal organs." (PMID 34064450, 2021). "IGF2R was also known as cation-independent mannose-6-phosphate receptor (CI-M6PR), was discovered to participate in both autophagy and tumor biology." (PMID 34365465, 2021). "The treatment effect was IGF2R-specific as the control mAb MOPC-21 radiolabeled with the same activity of 177Lu, had significantly less effect on the tumor growth rate (P = 0.06)." (PMID 31391495, 2019).